PRH2 (proline rich protein HaeIII subfamily 2)
Description:
PRP's act as highly potent inhibitors of crystal growth of calcium phosphates. They provide a protective and reparative environment for dental enamel which is important for the integrity of the teeth.
Synonyms: Pr; PRP-1/PRP-2; pr1/Pr2
Tractability: Antibody: UniProt places it where antibodies can reach, with medium confidence; UniProt predicts a signal peptide or a membrane-spanning region; its Gene Ontology location is reachable by antibodies, with medium confidence.
Gene: Protein-coding gene on chromosome 12 (10,929,236 to 10,934,845, forward strand). Ensembl gene ENSG00000134551.
Subcellular location: Secreted
Gene Ontology:
Molecular function: protein binding
Cellular component: extracellular region
Genetic constraint (gnomAD): Loss-of-function variants: 19 observed, 19.66 expected, observed/expected ratio (o/e) 0.97, 90% interval 0.67 to 1.42. The synonymous counts are far from expectation, so gnomAD's model fits this gene poorly and the ratio says little. Missense variants: 109 observed, 177.79 expected, observed/expected ratio (o/e) 0.61, 90% interval 0.52 to 0.72. Synonymous variants: 45 observed, 64.96 expected, observed/expected ratio (o/e) 0.69, 90% interval 0.55 to 0.89.
Homologues: Orthologues: chimpanzee PRH2 (99% identical). Paralogues in human: PRH1 (98% identical), PRB3 (63% identical), PRB2 (63% identical), PRB4 (58% identical), PRB1 (55% identical), PRR4 (36% identical).
Diseases named in the same sentence as PRH2 in open-access papers:
PRH2 is named in the same sentence as 6 diseases in open-access papers, as found by Europe PMC text mining. Sharing a sentence is not in itself a finding about the gene and the disease. The quoted sentences say what the papers report.
dental caries (1 paper, 2021). The decay of a tooth, in which it becomes softened, discolored, and/or porous. "PRH2, which showed 88.3% specificity, is a proline-rich acidic protein, and it can mediate bacteria adhesion to the teeth, resulting in dental caries." (PMID 33545363, 2021).
lung adenocarcinoma (1 paper, 2022). A carcinoma that arises from the lung and is characterized by the presence of malignant glandular epithelial cells. "GTF2E2 (general transcription factor IIE subunit 2) was found upregulated in lung adenocarcinoma tissue and was negatively associated with patients’ overall survival and the genetic mutations of PRH2 (proline-rich protein HaeIII subfamily 2) were also identified in lung cancer tissue." (PMID 35954157, 2022).
cancer (1 paper, 2022). A tumor composed of atypical neoplastic, often pleomorphic cells that invade other tissues. "Some genes always selected by each method were found (COPS7B, DONSON, GTF2E2, HAUS8, PRH2, and ZNF18) with known roles in cancer formation and progression." (PMID 35954157, 2022).
infection (1 paper, 2024). The state of being infected such as from the introduction of a foreign agent such as serum, vaccine, antigenic substance or organism. "We therefore examined those adolescents with markedly high S. mutans levels at baseline alone and at 17 years of age in association with caries and infection with high-cariogenicity mixed or B-1 types and human PRH1, PRH2 susceptible or resistant phenotypes." (PMID 38364699, 2024). "In addition, in that study, caries progression with the PRH1, PRH2 phenotypes P4a, P6, and P1 varied by infection status (+, –) with S. mutans and lactobacilli." (PMID 38364699, 2024).
PRH2 also shares sentences with these, for which no sentence is quoted: lung carcinoma (1 paper); Renal Cell Cancer (1).